CLDN4 (claudin 4)
Diseases named in the same sentence as CLDN4 in open-access papers (continued):
Sharing a sentence is not in itself a finding about the gene and the disease.
infection (continued). "In the present study, treatment with curcumin and infection with RSV, downregulated p63 and upregulated CLDN-1 and CLDN-4, and CLDN-4 and OCLN, respectively, in HNECs." (PMID 28883651, 2017). "In contrast, VD3 sufficient addition remarkably up-regulated the protein levels of Claudin-4 as well as ZO-1 (P < 0.05) and trended to increase the Claudin-1 protein amount (P = 0.061) regardless of infection." (PMID 35619956, 2022). "To correct this, in the present study, we investigated the role of claudins, especially Cldn-4 and luCldn-18, in host protection and immune response against infection with C. deneoformans using mice genetically lacking either Cldn-4 or luCldn-18." (PMID 34702961, 2021). "The inhibitors of COX1 and COX2 did not affect upregulation of claudin-4 and occludin after infection with RSV in Western blotting." (PMID 24058438, 2013). "In addition, the relative gene expression of the tight junction genes Ocln, Zo-1, and Cldn4 before or after infection did not significantly differ between the two types of colonoids." (PMID 34580592, 2021). "In addition, the fungal burdens in the lungs were not significantly different between Cldn-4+/+ and Cldn-4−/− mice on day 14 post-infection." (PMID 34702961, 2021). "We therefore investigated whether RSV-infection upregulated OCLN and CLDN-4 via p63 in hTERT-HNECs." (PMID 28883651, 2017). "Levels of Cldn4, which is phylogenetically related to Cldn13, were similar between all strains with marginal but significant differences only noted between BALB/c and C57BL/6 prior to infection, and between AJ and C57BL/6 on day 17 (1.3 fold higher in C57BL/6; p≤0.02, at both time points)." (PMID 20844758, 2010). "Mcat-induced upregulation of claudin (CLDN4), which could result in decreased paracellular permeability, suggests that epithelial cells resist paracellular invasion during Mcat infection, but not NTHi infection." (PMID 40492732, 2025). "Similar to the CLDN-4 mRNA results, flow cytometry showed that also the overall CLDN-4 protein expression levels were not altered by Ct infection at any studied time point." (PMID 34684219, 2021). "The upregulation of claudin-4, occludin and PKR after infection with RSV was not affected by any dose of salubrinal." (PMID 24058438, 2013).
adenocarcinoma (13 papers, 2011 to 2025). A common cancer characterized by the presence of malignant glandular cells. "Biomarkers that are most commonly used for this purpose include mesothelial (calretinin, D2-40, WT1 and cytokeratin 5/6), epithelial (Claudin 4), and adenocarcinoma markers (Ber-EP4, TTF-1, CEA, MOC31, Napsin A)." (PMID 36292206, 2022). "Claudin-4 was used as a reference for comparison with the p16 results since it is considered as the most sensitive marker to distinguish adenocarcinomas from reactive and malignant mesothelial cells in cytology of effusions." (PMID 32178642, 2020). "The epithelial markers E-cadherin, claudin-3 and claudin-4, commonly decreased in human adenocarcinomas are actually up regulated during ovarian carcinogenesis." (PMID 25278811, 2014). "Compared to bronchial cells claudins 1, 3 and 4 and 7 were decreased and claudin 5 mRNA increased in adenocarcinoma while when compared to lung parenchyma claudin 4 mRNA was increased but claudin 5 decreased." (PMID 21619599, 2011). "Claudin 4 mRNA is upregulated to 3-4 fold level in squamous, adenocarcinoma and small cell carcinoma compared to normal lung." (PMID 21619599, 2011). "Since adenocarcinoma metastases many times express claudin 4, CPE could potentially be used in treatment of such adenocarcinoma metastases in pleural cavity since benign mesothelial cells do not express this tight junctional protein." (PMID 21619599, 2011). "Similarly, studies of lung biopsy tissue showed that adenocarcinoma tumors had the highest staining of CLDN4 and atypical adenomatous hyperplasia cells had higher scores compared to the normal alveolar epithelium, which also indicated that CLDN4 is involved in the early tumorigenesis process." (PMID 38731853, 2024). "Two cases of CEA-negative adenocarcinoma, one of which was negative for Claudin 4 too, showed MUC4 expression (immunohistochemical score of 2+ or 3+)." (PMID 29317712, 2018). "Moreover, 3 cases of Claudin 4-negative adenocarcinoma, two of which were negative for CEA too, showed MUC4 expression (immunohistochemical score of 1+ or 2+)." (PMID 29317712, 2018). "There was one adenocarcinoma case which was negative for both CEA and Claudin-4 but positive MUC4 expression." (PMID 29317712, 2018).
inflammation (2 papers, 2014 to 2022). Aberrant reaction of the microcirculation characterized by movement of fluid and leukocytes from the blood into extravascular tissues. "Therefore, the decrease of claudin-4 in our study contributes to the disturbed sealing function in FAE after the TNF challenge, representing a weakened barrier in PPs during intestinal inflammation." (PMID 35707009, 2022).
colon (1 paper, 2021). "The increase in the barrier properties of IPEC-J2 cells upon their incubation with DMH was accompanied by a significant increase in the level of claudin-4, which was also significantly increased in tumors of the colon of DMH-induced rats." (PMID 34638619, 2021).
colorectal (1 paper, 2023). "In human CRC, an early step in TEI is the post-transcriptional downregulation of CLDN7 and CLDN4, which contributes to the penetration of bacteria and their inflammatory products; loss of CLDN7 has been shown to promote colorectal inflammation and tumorigenesis." (PMID 37542051, 2023).
neurodevelopmental disorder (1 paper, 2024). A behavioral and cognitive disorder with onset during the developmental period that involves impaired or aberrant development of intellectual, motor, or social functions. "The protein is a component of the tight junction complex, and chromosomal microdeletions including the Claudin-3 and Claudin-4 genes are associated with Williams–Beuren syndrome, a neurodevelopmental disorder affecting multiple systems." (PMID 38338705, 2024). "Of note, claudin-4 has been associated with Williams–Beuren syndrome (WBS), a neurodevelopmental disorder, with unusual facial features including a broad forehead, underdeveloped chin, and short nose." (PMID 38338705, 2024).
CLDN4 also shares sentences with these, for which no sentence is quoted: Crohn disease (4 papers); acantholytic disorders (3); endometrioid adenocarcinoma (3); head and neck squamous cell carcinoma (3); renal carcinoma (3); acute lung injury (2); collagenous colitis (2); invasive ductal carcinoma (2); peritoneal carcinoma (2); acromegaly (1); acute respiratory distress syndrome (1); adenomyosis (1); amyotrophic lateral sclerosis (1); anaplastic thyroid cancers (1); bacteremia (1); benign cystadenomas (1); brain cancer (1); breast carcinoma in situ (1); carcinosarcoma (1); clear cell carcinomas (1); clear cell renal cell carcinoma (1); colon adenocarcinoma (1); cryptorchidism (1); dendritic cell sarcoma (1); diabetes insipidus (1); diabetic nephropathy (1); distal renal tubular acidosis (1); endometrial tumors (1); enteritis (1); gallbladder adenocarcinoma (1).
A further 39 diseases each share a sentence with CLDN4 in 1 paper.